Y_RNA (Y RNA )
Gene: Miscellaneous RNA gene on chromosome 6 (119,057,880 to 119,057,974, forward strand). Ensembl gene ENSG00000222649.
Homologues: Orthologues: chimpanzee Y_RNA (99% identical). Paralogues in human: RNY4P7 (85% identical), RNY4 (84% identical), RNY4P3 (84% identical), Y_RNA (84% identical), RNY4P14 (83% identical), Y_RNA (83% identical), RNY4P17 (82% identical), RNY4P6 (82% identical), Y_RNA (82% identical), RNY4P23 (81% identical), RNY4P25 (81% identical), Y_RNA (81% identical), and 92 more.